TDRP (testis development related protein)
Description:
Contributes to normal sperm motility, but not essential for male fertility.
Synonyms: C8orf42; INM01; TDRP1; TDRP2
Tractability: No criterion of Open Targets' tractability assessment is met for any kind of drug.
Gene: Protein-coding gene on chromosome 8 (489,803 to 545,781, reverse strand). Ensembl gene ENSG00000180190.
Subcellular location: Nucleus; Cytoplasm
Subcellular location (Human Protein Atlas): Cytosol; Vesicles
Gene Ontology:
Biological process: spermatogenesis
Cellular component: cytoplasm; cytosol; mitochondrion; nucleus
Genetic constraint (gnomAD): Loss-of-function variants: 11 observed, 9.21 expected, observed/expected ratio (o/e) 1.19, 90% interval 0.75 to 1.82. That is too few expected variants to judge how well the gene tolerates losing a copy. Missense variants: 341 observed, 210.8 expected, observed/expected ratio (o/e) 1.62, 90% interval 1.48 to 1.77. Synonymous variants: 134 observed, 89.34 expected, observed/expected ratio (o/e) 1.5, 90% interval 1.3 to 1.73.
Homologues: Orthologues: macaque TDRP (97% identical), chimpanzee TDRP (90% identical), dog TDRP (76% identical), mouse Tdrp (75% identical), rat Tdrp (74% identical), pig TDRP (71% identical), rabbit TDRP (69% identical), guinea pig TDRP (67% identical), tropical clawed frog tdrp (58% identical), zebrafish si:ch211-225h24.2 (27% identical).
Diseases named in the same sentence as TDRP in open-access papers:
TDRP is named in the same sentence as 7 diseases in open-access papers, as found by Europe PMC text mining. Sharing a sentence is not in itself a finding about the gene and the disease. The quoted sentences say what the papers report.
nematode infection (1 paper, 2017). "CLE41p:GUS, TDRp:GUS and WOX4p:GUS transgenic Arabidopsis lines were infected with BCN and examined during nematode development to see if nematode infection could induce the expression of these genes at the feeding site." (PMID 28158306, 2017).
cancer (1 paper, 2015). A tumor composed of atypical neoplastic, often pleomorphic cells that invade other tissues. "GPCPD1 and TDRP genes have not been associated with cancer cell proliferation." (PMID 26310847, 2015).
infection (1 paper, 2017). The state of being infected such as from the introduction of a foreign agent such as serum, vaccine, antigenic substance or organism. "By following the same infection site, TDRp:GFP expression was monitored at 1 dpi and 2 dpi." (PMID 28158306, 2017).
TDRP also shares sentences with these, for which no sentence is quoted: age-related macular degeneration (1 paper); chlamydia (1); geographic atrophy (1); tumour (1).